CD44 (CD44 molecule (IN blood group))
Diseases named in the same sentence as CD44 in open-access papers (continued):
Sharing a sentence is not in itself a finding about the gene and the disease.
cancer (continued). "Hyaluronic acid (HA) has been previously used in this manner to protect proteins from degradation but in addition also as active ligand to target cancer cells since many of them overexpress the HA receptor, cluster-differentiation 44 (CD44)." (PMID 28706754, 2017). "The NPs were designed to selectively target CD44-overexpressing (e.g. ovarian) cancer cells, and HA served both as the hydrophilic block of the amphiphilic copolymer, and as the active targeting ligand." (PMID 28212584, 2017). "Additional T-47D luminal cancer cell line poor in CD44+/CD24−/low population was also tested in vivo presenting no impact of TRIM28 downregulation on xenograft growth." (PMID 27845900, 2017). "In this study, it was shown that CD146 induced an increased expression of CD44 but also a decreased expression of CD24 on the cell membrane suggesting that cancer cells acquire a cancer stem cell-like phenotype." (PMID 31548532, 2017). "PCa cancer stem/progenitor cells and metastasis are inhibited by miR-34a through the direct repression of CD44, a major adhesion molecule of the extracellular matrix, which is also a marker of CSCs." (PMID 28430640, 2017). "In our study, we found that the differential expression of Myc in RU/RR cells regulates cancer stem-like features (size of the CD44+/CD24− cell population, resistance to cisplatin and serial mammosphere ability) in TNBC." (PMID 28427212, 2017). "Compared with normal cells, CD44 showed a higher expression level in many cancer cells and was recognized as a potential therapeutic target in cancer therapy." (PMID 28068992, 2017). "More interestingly, the post-chemotherapeutic percentage of CD44+/CD24− cancer stem cell in HER2+ tumors is reduced from 10% at baseline to under 8% after 6 weeks of lapatinib therapy." (PMID 28445439, 2017). "Further interest arose with the description of CD44 as a marker for cancer stem cells in various carcinoma entities including breast, colon, hepatocellular carcinomas, head and neck, lung and pancreatic cancers." (PMID 27683128, 2017). "Previous studies have demonstrated increased cell survival following CD44 activation in several different cancers." (PMID 28380429, 2017). "The cancer stem cell content of the knockdown cells was analysed by quantifying the sub-population of CD44+/CD24− cells, which has been reported to be highly enriched in CSCs51." (PMID 28345629, 2017). "This is also accompanied by increased expression of CXCL12, CXCL10, as well as markers of cancer progression, including CD44, ZEB1 and vimentin." (PMID 28445977, 2017). "Here, we report that human CD44+/CD24− cancer cells are genetically highly unstable because of intrinsic defects in their DNA-repair capabilities." (PMID 28092266, 2017). "There are a variety of cell surface markers used to identify and enrich CSCs from different human cancers, such as CD44, CD24, CD29, CD133 and epithelial cell adhesion molecule (EpCAM)." (PMID 28969077, 2017). "To study the sensitivity of BCSCs to 5-FU treatment, we firstly separated the cancer stem cell population of CD44+/CD24-/low phenotype in T-47D and SKBR3 cell lines." (PMID 29371950, 2017). "Our in vitro data strongly suggests that RR cells are enriched with cells expressing CD44, a marker of cancer stem cells in TNBC." (PMID 28427212, 2017). "β-Catenin and TG2 was also upregulated in SW620 spheroid cells enriched with cancer stem cell marker CD44 and TG2 inhibition/knockdown reduced the spheroid forming potential of SW620 cells." (PMID 28223538, 2017). "It has been reported that CD44, the major hyaluronan (HA) receptor and one of the cancer stem cell (CSC) markers, is a novel partner for Podoplanin." (PMID 28912668, 2017). "Taken together, our study demonstrated that miR-520b inhibits the malignancy of HNC through regulation of cancer stemness conversion by targeting CD44." (PMID 28515423, 2017).
cancer (continued). "TGF-β is not only produced by CD44+/CD24− cells but it is among the many factors that mediate the communication between the cancer cells and their surrounding stroma (Massagué, 2008)." (PMID 28092266, 2017). "The role of NFκB signaling in GBM recurrence is consistent with its proposed role in GBM initiating cell (GICs) biology and proliferation, which is thought to be due to NFκB-dependent regulation of cancer stem cell genes, including CD44 and cyclin D1." (PMID 28556811, 2017). "We investigated the effect of Cd on TGF-beta-induced chemoresistance in SKOV-3 cancer stem cells with CD44+ (positive) and CD117+ (positive) population." (PMID 29340100, 2017). "Other oncogenes or cancer-associated genes such as CCNE1 (19q12; O15), CD44 (11p13; Y21), CDK6 (7q21.2; Y11), GATA4 (8p23.1-p22; O19), and GATA6 (18q11.2; O17) were also located in regions with high copy number gains." (PMID 29190909, 2017). "Transferrin, epidermal growth factor receptor (EGFR), folate receptor, CD44 (known as HCAM or homing cell adhesion molecule) receptor, integrins, and low density lipoprotein receptors are commonly exploited for targeted drug delivery in cancer cells." (PMID 28346381, 2017). "Here, we provide a possible mechanism by which CD146 suppresses BC progression as a target of CD44-downstream signaling, regulating neovascularization and cancer cell motility." (PMID 29121955, 2017). "The MKN45 cell line possesses multi-potentiality for differentiation and produces a large population of CD44-positive cancer stem cells." (PMID 29259235, 2017). "CD44, a cell adhesion protein, involves in various process in cancer such as cell survival and metastasis." (PMID 28523716, 2017). "These signaling pathways using CD44 as an upstream regulator function cooperatively to control downstream gene expression for cancer cell proliferation and cell cycle progression." (PMID 28099921, 2017). "In such a case, we can also develop additional OAds targeting CSCs by focusing other cancer stem cell markers, such a CD44 or CD24." (PMID 29100290, 2017). "While the current focus is on CSCs that are marked by CD133 and CD44, our results reinforce incongruous reports of stem cell-like characteristics in cancer cells that lack expression of these antigens." (PMID 28145883, 2017). "To further clarify the effect of RORβ on CCICs, we observed the tumorigenicity in vivo, the change in the colosphere number and the ratios of CD44 + CD24+ cancer-initiating cells in cells with overexpression of RORβ." (PMID 28137278, 2017). "To approach the clinical significance of miR-520b and CD44 in cancer, we performed prognostic analyses using datasets available online." (PMID 28515423, 2017). "CD44v6 is more specifically expressed in cancer tissues, but CD44 has an ubiquitously expression pattern." (PMID 28030817, 2017). "CD44 is well known to be a potential cancer stem cell marker in various cancers, e.g. in carcinomas of breast and ovary." (PMID 28404888, 2017). "The CSC population in breast and several other cancer types are defined by the expression of certain cell surface markers including CD44, CD133, ALDH1 and ESA." (PMID 29383121, 2017). "It should be noted that two cancer markers, CD44 and Bone Morphogenic Protein 4 (BMP4), were differentially found in the three sets of Caco-2 differentiated datasets and absent in normal cells." (PMID 28726765, 2017). "High resistance to anticancer drug in SNU354, SNU449 and Sk-Hep-1 seems related with the expression of CD44, a cancer stem cell marker in liver cells whereas responses to CVV in HCC does not." (PMID 29069721, 2017). "We also found leptin to increase the stemness of both cancer cell lines, as indicated by aldefluor activity, CD44/CD24 expression, and mammosphere formation." (PMID 28542577, 2017).
cancer (continued). "In the present study, we evaluated the expression of four cancer stem cell markers CD44, CD133, SOX2, Nanog in a large cohort of palatal MEC patients and identified some effective combinations of markers that have prognostic value for palatal MEC patients." (PMID 28262804, 2017). "CD44 is a cell surface adhesion receptor that is highly expressed in many cancers and regulates metastasis via recruitment of CD44 to the cell surface." (PMID 28326306, 2017). "The system was able to selectively induce cytotoxicity in CD44+ cancer cells after only 6 h of sample incubation which is a significant improvement from our previous DDS." (PMID 28706754, 2017). "It has been shown that CD44+/CD24− cancer cells are more adept at forming tumors, are more resistant to chemotherapy and tend to have greater metastatic potential." (PMID 28092266, 2017). "Our results showed that the protein expression of ALDH1 was positively stained in the cytoplasm, whereas BMI1 was in the cytoplasm and nucleus in SCCHN; CD44 was mainly expressed in the membrane of cancer cells but also in the basal layer of normal mucosa." (PMID 28865486, 2017). "To further validate our findings, we used a second independent approach to quantitate “stemness” in cancer cells, by employing specific cell surface markers, namely fluorescent antibody probes directed against CD44 and CD24." (PMID 29253841, 2017). "CD44 is an important cell surface marker for isolating CSCs from tumors and is correlate with poor prognosis in various human cancers." (PMID 28070170, 2017). "Several studies have demonstrated that CD44 can be used to isolate cancer cells with stem cell-like and cancer-initiating properties from other populations of cancer cells." (PMID 28070170, 2017). "The ovarian cancer cells that express CD44+ exhibit cancer stem cell-like properties of migration and chemo-resistance." (PMID 28417924, 2017). "HA served as the hydrophilic block, and as the ligand for actively targeting cancer cells overexpressing CD44." (PMID 28212584, 2017). "In previous reports, CD44 expression has been linked to chemoresistance based on ABC transporter overexpression including ABCB1 and ABCC2 in various tumors especially in the cancer stem cell compartment." (PMID 29371972, 2017). "In response to the extracellular microenvironment, CD44 is a unique adhesion molecule that plays an essential role in cancer cell migration and matrix adhesion." (PMID 29340052, 2017). "We further showed that GDF15 facilitated the conversion of cancer stemness, as assessed by the promotion of CD44+ and ALDH1+ cell populations and spheroid cell formation." (PMID 27903972, 2017). "In fact, cancer cells with positive CD44, which interact with the cysteine transporter xCT and promote GSH synthesis, exhibit grow advantage and resistant to certain therapy." (PMID 28245869, 2017). "The top five up-regulated cancer stemness associated genes include: SNAI2 (SLUG) (8.2 folds), SOX9 (6.4 folds), ITGB3 (integrin β3) (5.4 folds), CD44 (4.3 folds) and MET (2.9 folds) (DU145FP vs. DU145WT)." (PMID 28698547, 2017). "The hyaluronate receptor CD44 is a type I transmembrane glycoprotein commonly used as a marker to identify cancer stem/initiating cells." (PMID 28851445, 2017). "LACHA-DOX has several exceptional features such as high stability, high tolerability, fast glutathione-responsive drug release, and superior selectivity toward CD44 that is overexpressed in several human hematological cancer cells as well as cancer stem cells." (PMID 28958164, 2017). "Multiplex transcriptome profiling of single CTCs revealed presence of sub-populations of CTCs expressing multiple pro-cancer transcripts including cancer stem cell markers such as CD44 and CD24." (PMID 28626429, 2017). "Several studies demonstrated CD44 ablation enhanced the effect of chemotherapeutic drugs in cancer cells." (PMID 29029419, 2017).
cancer (continued). "In cancer progression, hyaluronan acts as a principle ligand, binding to receptors including CD44 and RHAMM." (PMID 28282922, 2017). "Recent studies have discussed the relationship between CD44 expression on cancer cell surface and activation of Matrix Metalloproteinases (MMPs)." (PMID 29121955, 2017). "Here, we developed a CD44-targeted polymeric nanocomplex by encapsulating 10-hydroxycamptothecin (HCPT) into hyaluronic acid nanoparticles (HANP) for targeted cancer therapy." (PMID 29097925, 2017). "We concluded that miR-520b inhibits malignancy of HNC through the regulation of cancer stemness by targeting CD44." (PMID 28515423, 2017). "Surprisingly, DPI treatment selectively depleted the CSC sub-population (CD44+/CD24-) from the total cancer cell population." (PMID 29253841, 2017). "ESCC cancer stem cells express high levels of CD44; cancer cells with high CD44 expression show typical features of EMT." (PMID 28930282, 2017). "Results of this experiment demonstrated decrease in CD24 and CD44 expressions in carcinomas, on the other hand increase in ALDH1 after treatment with CLOs." (PMID 28524540, 2017). "Previously, many alternative splicing variants had been observed in cancer, for examples, EGFR, CD44, NER and BRCA1." (PMID 27557076, 2016). "CD44 normally takes part in cell-cell and cell-matrix adhesion interactions, which is involved in cancer cell migration, proliferation and metastasis." (PMID 27340862, 2016). "CD44 is a receptor for hyaluronic acid and influences many characteristics of cancer cells, including stemness." (PMID 27351130, 2016). "Based on these findings, we predicted that CD44 would have a significant impact on the pathogenesis and prognosis of many cancer types." (PMID 27738347, 2016). "It is well documented that up-regulation of CD44 on cancer cells is correlated with poor prognosis as it can enhance cell migration and metastasis." (PMID 27329592, 2016). "CD44, the hyaluronic acid (HA) receptor, is upregulated on the surface of cancer cells and on activated hepatic stellate cells (aHSCs) rather than normal cells." (PMID 28029125, 2016). "Targeting CD44 using monoclonal antibody-mediated pathways is a novel targeted therapy in cancer treatment." (PMID 27200096, 2016). "P-gp and CD44 are co-regulated, co-immunoprecipitated, and their interaction promotes cell migration and invasion in cancer." (PMID 26938523, 2016). "Then we examined the expression of epithelial marker ZO-1 and cancer stemness markers (CD44 and CD133) in OC cells after the knockdown and overexpression of miR-137 and miR-34a, using qPCR assays." (PMID 27596137, 2016). "There was less percentage of CD133-positive and CD44-positive cancer cells in the Ad-Bmi-1i-treated xenograft tissues than in control group, suggesting a potential inhibitory or killing role of Ad-Bmi-1i for gastric CSCs." (PMID 27009837, 2016). "Given the important functions of CD44 in cell-cell and cell-matrix interactions, CSCs are usually postulated to play a vital role in cancer metastasis and aggressiveness." (PMID 26821610, 2016). "Several studies similarly utilised CD44 positivity to isolate cells with stem cell-like and cancer-initiating properties from other cancer cells." (PMID 27330410, 2016). "HCC1937/wt BRCA1 cells showed the presence of a distinct CD44high/24–population (3.07 ± 1.12 %) within its CD44+/24–/low (30.6 ± 5.0 %) putative cancer stem cell population." (PMID 27229859, 2016). "Although we did not observe significant changes in drug-treated neutrophil PSGL-1 expression (data not shown), pravastatin is known to affect another E-selectin rolling ligand CD44 expression in cancer cells by increasing CD44 shedding." (PMID 27381673, 2016). "Caution is needed when interpreting the data in the attempt to elucidate the precise role of CD44 in cancer." (PMID 27148537, 2016). "In summary, the cancer stem cell biomarker CD44 and Shh signaling pathway signatures can be used as novel diagnostic and therapeutic tools." (PMID 26839535, 2016).
cancer (continued). "In prostate cells, SND1 recruits splicing factor SAM68 and other spliceosomal components on CD44 pre-mRNA, promotes the inclusion of CD44 variable exons, which correlates with increased proliferation, motility, and invasiveness of cancer cells." (PMID 26808625, 2016). "Based on these roles in cancer development, molecular mechanisms contributing to the regulation of CD44 and/or function have been under intensive investigation." (PMID 28000766, 2016). "Several studies have demonstrated that increased CD44 expression activates several signalling pathways related to cancer progression and metastasis, including Shh pathway." (PMID 26839535, 2016). "We have previously reported that E-selectin expression on the endothelial cell surface mediates shear-resistant adhesion and migration of circulating cancer cells via interaction with CD44." (PMID 27220365, 2016). "In this study, we used cancer stem cell surface marker CD44+/CD24-/low, a first described marker for BCSCs, and embryonic stem cell markers Oct3/4, Sox II and Nanog to determine the putative cancer stem cells." (PMID 27036550, 2016). "Another macrophage-derived proinflammatory cytokine TNF was demonstrated to be important for the induction of cancer stem cell marker CD44 overexpression on ccRCC tumor cells." (PMID 27807511, 2016). "HA-based nanoformulations have been used successfully in cancer therapy due to the binding of CD44, an HA receptor that is highly expressed in cancer cells, including cancer stem cells." (PMID 28029125, 2016). "ADAM10 is reported as a sheddase that can cleave transmembrane proteins such as amyloid precursor protein (APP), E-cadherin, N-cadherin, CD44 and Notch, all of which play a significant role in proliferation, migration, invasion or stemness of cancer cells." (PMID 27259866, 2016). "Its overexpression in gastric, ovarian and in pancreatic cancer with high peritoneal seeding potential indicates a putative role for CD44 in PM formation." (PMID 27074785, 2016). "We first purified CSCs by FACSort using the cancer stem cell markers ESA+CD24+CD44+; a marker for the murine MHC class I molecule, H-2Kd, was also included to enable identification and exclusion of murine stromal cells from the analysis." (PMID 27330806, 2016). "In summary, we show that the aggressive clones derived from CD49f+/CD44+/CD24− single cells activate the OCT4/SOX2/lincRNA-RoR signaling axis to maintain cancer stem cell self-renewal and regulate differentiation." (PMID 27374087, 2016). "The expression levels of the cancer stem cell‐specific markers CD44, CD133, and ABCG2, the tumor suppressor genes p21 and p16, and the endoplasmic reticulum (ER) stress‐related genes IRE1, GRP78/BIP, and ARTC were determined by quantitative PCR." (PMID 27239442, 2016). "Strikingly, the few data showing association come from cancer stem cell research: CD90, CD44, and CD166 are notably considered cancer stem cell markers." (PMID 27465541, 2016). "The most considerable advantage of HA is its strong affinity for CD44, a cell surface protein which is overexpressed in many cancer cells and cancer stem cells." (PMID 27473554, 2016). "In vitro and ex vivo blocking experiments in several types of cancer illustrated the role of CD44 as adhesion molecule in PM formation and particularly indicated a role for the CD44 s splice variant." (PMID 27074785, 2016). "CD44 is one of the commonly recognized stem cell markers, which plays a critical role in many cancer related cellular processes." (PMID 27738347, 2016). "This novel phototheranostic strategy provides a promising opportunity for the destruction of CD44-positive populations that include cancer stem-like cells, in locally advanced primary and metastatic TNBC." (PMID 27302409, 2016). "The prospect of CSC identification based on the expression of specific surface markers opened the way to their detection in other solid tumours: brain and lung (CD133+), prostate, gastric, and ovarian (CD44+) cancers, among others." (PMID 27766946, 2016).